AGRN (agrin)
Description:
Depending on alternative splicing and post-translational modifications, it has a role in different processes, including neuromuscular junction formation and maintenance, and regulation of neurite outgrowth (By similarity). Also involved in positive regulation of cartilage formation through alpha-dystroglycan binding and up-regulation of SOX9. [Isoform 1]: Heparan sulfate basal lamina glycoprotein that plays a central role in the formation and the maintenance of the neuromuscular junction (NMJ) and directs key events in postsynaptic differentiation. Component of the AGRN-LRP4 receptor complex that induces the phosphorylation and activation of MUSK. The activation of MUSK in myotubes induces the formation of NMJ by regulating different processes including the transcription of specific genes and the clustering of AChR in the postsynaptic membrane. Calcium ions are required for maximal AChR clustering. AGRN function in neurons is highly regulated by alternative splicing, glycan binding and proteolytic processing. Modulates calcium ion homeostasis in neurons, specifically by inducing an increase in cytoplasmic calcium ions. Functions differentially in the central nervous system (CNS) by inhibiting the alpha(3)-subtype of Na+/K+-ATPase and evoking depolarization at CNS synapses. This secreted isoform forms a bridge, after release from motor neurons, to basal lamina through binding laminin via the NtA domain. [Isoform 2]: Transmembrane form that is the predominate form in neurons of the brain, induces dendritic filopodia and synapse formation in mature hippocampal neurons in large part due to the attached glycosaminoglycan chains and the action of Rho-family GTPases. Isoform 1, isoform 4 and isoform 5: neuron-specific (z+) isoforms that contain C-terminal insertions of 8-19 AA are potent activators of AChR clustering. Isoform 5, agrin (z+8), containing the 8-AA insert, forms a receptor complex in myotubules containing the neuronal AGRN, the muscle-specific kinase MUSK and LRP4, a member of the LDL receptor family. The splicing factors, NOVA1 and NOVA2, regulate AGRN splicing and production of the 'z' isoforms. [Isoform 3]: Muscle-specific isoform, probably involved in endothelial cell differentiation. [Isoform 6]: Involved in the positive regulation of cartilage formation, acting through alpha-dystroglycan binding and up-regulation of SOX9, a transcription factor that plays a key role in chondrocytes differentiation. [Agrin N-terminal 110 kDa subunit]: Is involved in regulation of neurite outgrowth probably due to the presence of the glycosaminoglcan (GAG) side chains of heparan and chondroitin sulfate attached to the Ser/Thr- and Gly/Ser-rich regions. Also involved in modulation of growth factor signaling (By similarity). [Agrin C-terminal 22 kDa fragment]: This released fragment is important for agrin signaling and to exert a maximal dendritic filopodia-inducing effect. All 'z' splice variants (z+) of this fragment also show an increase in the number of filopodia.
Synonyms: CMS8; CMSPPD
Tractability: Antibody: UniProt places it where antibodies can reach, with high confidence; its Gene Ontology location is reachable by antibodies, with high confidence; UniProt predicts a signal peptide or a membrane-spanning region; the Human Protein Atlas places it where antibodies can reach. PROTAC: ubiquitination databases record sites on it; its protein half-life has been measured.
Gene: Protein-coding gene on chromosome 1 (1,020,120 to 1,056,119, forward strand). Ensembl gene ENSG00000188157.
Subcellular location: Secreted, extracellular space, extracellular matrix (Isoform 1); Synapse (Isoform 2); Cell membrane
Subcellular location (Human Protein Atlas): Cytosol; Plasma membrane; Predicted to be secreted
Pathways (Reactome):
Disease: Attachment and Entry; Defective B3GALT6 causes EDSP2 and SEMDJL1; Defective B3GAT3 causes JDSSDHD; Defective B4GALT7 causes EDS, progeroid type; Defective EXT1 causes exostoses 1, TRPS2 and CHDS; Defective EXT2 causes exostoses 2; Dengue Virus Attachment and Entry; Dengue Virus-Host Interactions; RSV-host interactions; Respiratory syncytial virus (RSV) attachment and entry
Extracellular matrix organization: ECM proteoglycans; Formation of the dystrophin-glycoprotein complex (DGC); Integrin cell surface interactions; Non-integrin membrane-ECM interactions
Metabolism: Glycosaminoglycan-protein linkage region biosynthesis; HS-GAG biosynthesis; HS-GAG degradation
Hemostasis: Initiation of coagulation cascade; Regulation of clotting cascade
Developmental Biology: NCAM1 interactions
Sensory Perception: Retinoid metabolism and transport
Gene Ontology:
Molecular function: protein binding; acetylcholine receptor regulator activity; calcium ion binding; chondroitin sulfate binding; dystroglycan binding; extracellular matrix structural constituent; heparan sulfate proteoglycan binding; laminin binding; sialic acid binding; structural constituent of cytoskeleton; transmembrane receptor protein tyrosine kinase activator activity; signaling receptor activator activity
Biological process: receptor clustering; chemical synaptic transmission; clustering of voltage-gated sodium channels; filopodium assembly; G protein-coupled acetylcholine receptor signaling pathway; nervous system development; neuromuscular junction development; positive regulation of synaptic assembly at neuromuscular junction; positive regulation of transcription by RNA polymerase II; signal transduction; synapse organization; animal organ development; cytoskeleton organization; membrane organization; synaptic signaling
Cellular component: basement membrane; extracellular exosome; extracellular matrix; extracellular region; gel phase of basement membrane; Golgi lumen; lysosomal lumen; plasma membrane; synapse
Genetic constraint (gnomAD): Loss-of-function variants: 106 observed, 170.64 expected, observed/expected ratio (o/e) 0.62, 90% interval 0.53 to 0.73. The synonymous counts are far from expectation, so gnomAD's model fits this gene poorly and the ratio says little. Missense variants: 3,017 observed, 2,654.3 expected, observed/expected ratio (o/e) 1.14, 90% interval 1.1 to 1.17. Synonymous variants: 1,516 observed, 1,170.5 expected, observed/expected ratio (o/e) 1.3, 90% interval 1.24 to 1.35.
Gene-disease validity (ClinGen):
ClinGen rates the evidence that AGRN causes each of these diseases.
congenital myasthenic syndrome 8 (autosomal recessive): Definitive. Any congenital myasthenic syndrome in which the cause of the disease is a mutation in the AGRN gene.
Homologues: Orthologues: chimpanzee AGRN (99% identical), macaque AGRN (96% identical), pig AGRN (86% identical), dog AGRN (85% identical), rat Agrn (83% identical), mouse Agrn (82% identical), guinea pig AGRN (80% identical), tropical clawed frog agrn (61% identical), zebrafish agrn (51% identical). Paralogues in human: LAMA1 (19% identical), HSPG2 (19% identical), LAMA2 (19% identical), LAMA5 (18% identical), LAMA3 (18% identical), USH2A (15% identical), LAMB2 (13% identical), LAMB1 (13% identical), LAMB4 (13% identical), LAMC3 (11% identical), LAMA4 (11% identical), LAMC1 (11% identical), and 15 more.
Diseases named in the same sentence as AGRN in open-access papers:
AGRN is named in the same sentence as 140 diseases in open-access papers, as found by Europe PMC text mining. Sharing a sentence is not in itself a finding about the gene and the disease. The quoted sentences say what the papers report.
sarcopenia (35 papers, 2012 to 2026). Progressive decline in muscle mass due to aging which results in decreased functional capacity of muscles. "Previous researches have confirmed that biomarkers related to the neuromuscular junction, such as the C-terminal agrin fragment and neurofilament light chain, are linked with sarcopenia and neural health." (PMID 40513379, 2025). "Previous studies have linked the AGRN gene variants with sarcopenia-related traits (muscle mass and strength) and congenital myasthenia." (PMID 36980932, 2023). "Agrin was identified as a marker for the diagnosis of sarcopenia and implicated in the pathogenesis of sarcopenia caused by degeneration of the NMJ." (PMID 37699519, 2023). "In this context, it should be noted that agrin-dependent sarcopenia can be distinguished from aging-associated muscle wasting." (PMID 36977974, 2023). "Further, serum levels of C-terminal agrin were reported to be associated with sarcopenia, and as an indicator of instability and loss of the NMJ." (PMID 36516485, 2022). "The agrin-based pharmacological approaches have been proposed as novel treatments for sarcopenia caused by age-related NMJ degeneration." (PMID 36233091, 2022). "Furthermore, higher serum agrin, which has been detected in older adults with sarcopenia, was associated with physical impairment." (PMID 37445634, 2023). "Therefore, the single-variant and gene-burden results complement the WGS data, illustrating that both common intronic and rare exonic AGRN/PRSS12 variants associate with phenotypes relevant to sarcopenia." (PMID 36609795, 2023). "Plasma CAFs have been found to be elevated in a subset of human sarcopenia patients, suggesting that uncontrolled degradation of agrin at the NMJ may contribute to age-associated neuromuscular decline." (PMID 28127382, 2017). "In light of the observations that Agrin levels decreased during aging and that loss of Agrin in skeletal muscle caused earlier onset of sarcopenia-like muscle deficits, we hypothesized that insufficient Agrin might be a mechanism of age-associated sarcopenia." (PMID 38461287, 2024). "Plasma levels of Dickkopf‐3 (Dkk‐3) and c‐terminal agrin fragment‐22 (CAF22) can suggest a sarcopenia phenotype in elderly individuals with respiratory diseases." (PMID 41582634, 2026). "Age-related NMJ remodeling involves proteolytic cleavage of Agrin into CAF, which inactivates cholinergic receptors in presynaptic membranes and promotes denervated muscle fiber accumulation—a hallmark feature of sarcopenia." (PMID 40219034, 2025). "Recently, C‐terminal agrin fragment (CAF) has been identified as an indicator for early diagnosis of sarcopenia." (PMID 39887577, 2025). "Experimental removal of agrin from muscle tissue induces premature signs of muscle aging and the development of sarcopenia." (PMID 41303670, 2025). "Altered CAF levels are considered potential biomarkers of NMJ instability in aging, reinforcing the concept of agrin’s role in the pathogenesis of human sarcopenia." (PMID 41303670, 2025). "Several biomarkers have been identified for sarcopenia, including the creatinine/cystatin C ratio, C-terminal agrin fragment, and multiple microRNAs (miR-7a-1-3p, miR-135a-5p, miR-151-5p, miR-196b-5p)." (PMID 40076542, 2025). "Surprisingly, in contrast to the elevated serum Agrin fragments observed in patients with sarcopenia, the expression of Agrin was found to be decreased in the skeletal muscles of aged mice." (PMID 38461287, 2024). "Collectively, our findings underscore the pivotal role of Agrin in the aging process of skeletal muscles and propose Agrin as a potential therapeutic target for addressing sarcopenia." (PMID 38461287, 2024). "We identified two variants, rs2710873 (AGRN) and rs71608359 (PRSS12), that were associated with sarcopenia phenotypes in the UKBB and GenoFit cohorts." (PMID 36609795, 2023).
sarcopenia (continued). "In animal models, impairment in the expression of the proteoglycan agrin produces phenotypic alterations resembling those observed in aged NMJs and sarcopenia." (PMID 37111070, 2023). "PhenoScanner was used to determine if AGRN and/or PRSS12 variants had previously been implicated with sarcopenia phenotypes." (PMID 36609795, 2023). "Notwithstanding the UKBB data, there are limited published data concerning the potential associations between AGRN/PRSS12 variants and sarcopenia phenotypes." (PMID 36609795, 2023). "Collectively, our findings support the relevance of agrin and neurotrypsin to sarcopenia, and provide novel evidence of the pertinence of AGRN and PRSS12 to sarcopenia phenotypes." (PMID 36609795, 2023). "Recently, the relevance of circulating C-terminal agrin fragment (CAF) as an accessible screening method alternative for sarcopenia has gained credence." (PMID 33993303, 2021). "An engineered agrin (a C-terminal fragment of mouse agrin) improved skeletal muscle strength in a sarcopenia-like murine muscle model (neurotrypsin-overexpression)." (PMID 34360831, 2021). "Experimental mouse models with impaired agrin expression show fragmented NMJs, mimicking aged NMJs and precocious sarcopenia." (PMID 33815879, 2021). "A sarcopenia mouse model previously generated by increasing cleavage of agrin at the NMJ (by overexpression of neurotrypsin) displayed a reduced grip strength, which was restored with treatment using NT1654." (PMID 31394789, 2019). "Here we demonstrate that the agrin biologic NT-1654 is capable of activating the agrin/Lrp4/MuSK system in vivo, leading to an almost full reversal of the sarcopenia-like phenotype in neurotrypsin-overexpressing (SARCO) mice." (PMID 24520420, 2014). "Consistent with this, both neurotrypsin and matrix metalloproteinase-3 (MMP-3) cleave agrin, and increased cleavage (or increased levels of cleavage fragments) has been proposed to promote age-related muscle decline, called sarcopenia." (PMID 23056392, 2012). "This hypothesis predicts that increasing Agrin expression could diminish sarcopenia-like deficits in aged muscles." (PMID 38461287, 2024). "Together, these results suggest that Yap signaling and α-DG, rather than MuSK signaling, are involved in the accelerated sarcopenia onset caused by Agrin deficiency." (PMID 38461287, 2024). "Pursuing this hypothesis, it would be intriguing to experiment with increasing Yap activity in aging and Agrin cKO mice to observe if it mitigates sarcopenia phenotypes." (PMID 38461287, 2024). "Furthermore, the conditional deletion of Agrin in skeletal muscle accelerated the onset of sarcopenia." (PMID 38461287, 2024). "Accordingly, we explored whether genes encoding agrin (AGRN) and neurotrypsin (PRSS12) were associated with sarcopenia phenotypes: muscle mass, strength and plasma C-terminal agrin fragment (CAF)." (PMID 36609795, 2023). "Evidently, although physiological studies have reported promising evidence supporting the relevance of agrin and neurotrypsin to sarcopenia, few studies have investigated whether this relevance remains at the gene level." (PMID 36609795, 2023). "Importantly, in both studies, the increased expression of AGRN was accompanied by phenotypic changes relevant to sarcopenia, such as NMJ fragmentation, reduction in muscle cross-sectional area and contractile potential, and denervation." (PMID 36609795, 2023). "In light of this, we aimed to determine whether AGRN and/or PRSS12 were associated with sarcopenia phenotypes including muscle mass, strength and plasma CAF levels." (PMID 36609795, 2023). "Accordingly, this study aimed to explore whether AGRN and/or PRSS12 are associated with sarcopenia phenotypes (muscle mass, strength and plasma CAF levels)." (PMID 36609795, 2023). "C-terminal Agrin Fragment (CAF) has emerged as a potent biomarker for identifying sarcopenia." (PMID 36977974, 2023). "Excessive cleavage of AGRN has been shown to evoke precocious sarcopenia." (PMID 33993303, 2021).
sarcopenia (continued). "Moreover, the agrin partner MuSK also decreases during sarcopenia, further supporting a key role of agrin-MuSK pathway during aging." (PMID 33815879, 2021). "Finally, while AGRN was the primary focus of this study, the potential benefits of combination models in increasing the sensitivity of sarcopenia diagnosis should be considered." (PMID 33993303, 2021). "Importantly, the C-terminal 22 kDa agrin cleavage fragment (CAF) is increasingly being investigated as a biomarker of age-related sarcopenia." (PMID 28824419, 2017). "Agrin fragment administration determined NMJ stabilization and phenotype amelioration in SARCO mice (experimental model of Sarcopenia, characterized by age-related muscle wasting), and accelerated reinnervation after sciatic nerve crush, by activating the agrin/Lrp4/MuSK system." (PMID 26869891, 2016). "Thus, agrin fragments appear to be not only promising candidates in the search for biomarkers in the field of sarcopenia diagnosis, but also carry hope for use as potential therapeutic agents." (PMID 24904412, 2014). "This could become important in the context of diagnosing and treating sarcopenia, given that with the appearance of agrin fragments, first biomarkers and therapeutic agents for a subset of sarcopenia are also apparent." (PMID 24904412, 2014). "However, it needs to be mentioned that only about 38% of the sarcopenia patients displayed elevated levels of the agrin fragment in serum, indicating that sarcopenia is indeed likely a multi-factorial disease." (PMID 24904412, 2014). "The phenotype of SARCO mice can be fully reversed by overexpression of a neurotrypsin-resistant version of agrin, suggesting that replenishment of agrin might be an option in the treatment of sarcopenia." (PMID 24520420, 2014). "Therefore, muscle Agrin emerges as a contributor to the pathogenesis of age-related sarcopenia, and suggest Agrin intervention in muscle holds promise as a novel therapeutic strategy for sarcopenia." (PMID 38461287, 2024). "Elevated serum levels of C-terminal agrin fragment (CAF) resulting from NMJ disassembly and denervation are associated with sarcopenia, pleading in favor of the hypothesis that the integrity of NMJs is essential for the preservation of both motor nerve and muscle fibers." (PMID 37111070, 2023). "In line with this, a potential wider range of effects of neuronal agrin emerges and the agrin-based pharmacological approaches proposed to counteract sarcopenia could have benefits not only stabilising the NMJ but also favouring the regenerative capability of myoblasts in the aged muscle." (PMID 36233091, 2022). "Therefore, modulation of muscle agrin signalling and/or NMJs may be a novel treatment of sarcopenia and neuromuscular disease." (PMID 28127382, 2017). "Indeed, upon sarcopenia and dystrophy, NMJs morphologically deteriorate and exhibit altered characteristics of primary signaling molecules, such as nicotinic acetylcholine receptor and agrin." (PMID 24904412, 2014). "Interestingly, CAFs are elevated in a subset of sarcopenia patients, suggesting that degradation of agrin at NMJs may contribute to sarcopenia." (PMID 24520420, 2014). "The serum C-terminal agrin fragment reflects NMJ disassembly and correlates with sarcopenia, supporting its utility for screening and longitudinal monitoring in older adults." (PMID 41303670, 2025). "Moreover, a recent literature review has highlighted how muscle depletion and sarcopenia are closely linked to neuromuscular degradation, a process quantifiable through the assessment of biomarkers indicating neuromuscular junction (NMJ) stability, such as the C-terminal agrin fragment (CAF)." (PMID 38565837, 2024). "In conclusion, despite the current dearth of evidence, AGRN and PRSS12 appear to be promising candidate genes for sarcopenia." (PMID 36609795, 2023).